MMP9 (matrix metallopeptidase 9)
Diseases named in the same sentence as MMP9 in open-access papers (continued):
Sharing a sentence is not in itself a finding about the gene and the disease.
Stroke (continued). "20-month-old male mice underwent 60-minute MCAO (n=7) or sham (n=5) surgery and flow cytometry was performed at 72 hours post-stroke to quantify relative protein expression of CD147 and MMP-9." (PMID 32191628, 2020). "In mice with hyperhomocysteinemia (HHcy), a vascular dysfunction and stroke-like condition, the protein levels of MMP-2 and MMP-9 were significantly higher than that of the control mice." (PMID 32466129, 2020). "Wang and his colleagues found that the MMP-9 expression and its colocalization level with pericytes were declined by the CORM-3 in the mouse stroke model." (PMID 32581781, 2020). "In the clinical setting, we previously showed that the circulating levels of neutrophil degranulation products (MMP-8, MMP-9, MPO and NE) peak in stroke patients receiving r-tPA during the first hour after drug administration." (PMID 32977685, 2020). "Pharmacological blockage of MMP-9 or MMP-9 gene deletion confers neuroprotection in traumatic brain injury and stroke." (PMID 32046035, 2020). "In the pathological progression of stroke, gelatinases including MMP-2 and MMP-9, possess the ability to activate numerous pro-inflammatory agents, including chemokine CXCL-8, interleukin 1β, and tumor necrosis factor α." (PMID 30953513, 2019). "The infarct volume, as well as serum levels of matrix metalloproteinase-9 (MMP-9) and interleukin-10 (IL-10), were measured one week after stroke." (PMID 31807255, 2019). "In a mouse stroke model, the presence of mouse CEACAM1 inhibits the MMP9-mediated damage to endothelial cells." (PMID 31849868, 2019). "As MMP-9 is the major subversive of the BBB, endothelial cells are considered to be the main target for the protection of the neurovascular unit following stroke." (PMID 30953513, 2019). "In this study, through bioinformatics analysis, we found that MMP9 is highly expressed and the PI3K/Akt signaling pathway is inactive in stroke samples." (PMID 30911000, 2019). "Members of the MMPs family, specifically MMP-2 and MMP-9 are involved in the breakdown of the BBB and increased levels of these MMPs have been observed during CIRI in stroke." (PMID 31057477, 2019). "Results from the present study showed that the increment of plasma MMP-9 and brain MMP-2 activity after stroke were significantly inhibited by the combination of DHI with t-PA." (PMID 29681849, 2018). "Myelin degradation following ischemic stroke is attenuated in MMP9 knockout mice, implicating MMP’s in post-stroke WM injury." (PMID 29896433, 2018). "In our study, Western blot analysis and an angiogenic ELISA array show that APX3330 treatment significantly decreases inflammatory factors such as MCP1, MMP9 and RAGE compared to control T1DM stroke rats." (PMID 29896433, 2018). "Reduced IgG extravasation and reduced MMP-9 and MMP-3 activity suggested that 1.0 mg/kg L-902,688 reduced stroke-induced BBB damage." (PMID 29527151, 2018). "APX3330 significantly decreases ischemic brain tissue expression of MMP9 and RAGE compared to PBS treated control T1DM stroke rats (p<0.001, n=4/group)." (PMID 29896433, 2018). "The aim of this study was to further investigate the influence of multisensory brain stimulation provided by EE after stroke on PNN integrity and on changes in expression/activity of MMP-2 and MMP-9, tPA, ADAMTS-4, and their inhibitors." (PMID 28290150, 2018). "We found that EP4 receptor activation with L-902,688 potently reduces levels of some of the key mediators of stroke-induced BBB damage including IL-1β, IL-6, MMP-3, and MMP-9." (PMID 29527151, 2018). "We recently showed that genetic deletion or pharmacological blockade of the EP1 receptor results in a dramatic reduction in stroke injury and BBB permeability, which correlated with reduced levels of MMP-3 and MMP-9." (PMID 29527151, 2018).
Stroke (continued). "After stroke onset, plasma MMP-9, PAI-1, and P-selectin were significantly elevated, and the combination of t-PA plus DHI significantly suppressed the plasma MMP-9, PAI-1, P-selectin levels compared with t-PA alone treatment." (PMID 29681849, 2018). "EP4 receptor activation similarly reduced stroke-induced MMP-9 and MMP-3 activity, particularly in the cortex, and stroke-induced MMP-9 mRNA levels." (PMID 29527151, 2018). "Our results in stroke patients highlight a remarkable presence of tPA, MMP-2, and MMP-9 activities in peri-infarct zones and most importantly in regions remote from the infarct." (PMID 28290150, 2018). "Current data suggest that MMPs (such as MMP-2 and MMP-9) mediate beneficial dendritic plasticity and ECM remodeling at delayed stages after stroke." (PMID 28290150, 2018). "D-4F treatment significantly (n=8/group, *p<0.05) decreases TLR4, MMP9 and nuclear NFκB expression compared to PBS treated T1DM stroke control rats at 48 hours after stroke." (PMID 29221142, 2017). "As comparison, in one of the original studies on stroke, a 9-gene signature was derived, including S100A12, ARG1 and MMP9 of our BRGs." (PMID 28771541, 2017). "Thus, ARG1 and MMP9 may be used in monitoring the recovery from stroke." (PMID 28771541, 2017). "We have shown before that MMP‐9 and MCP‐1 are reduced in ischemic stroke with post‐stroke BML‐111 administration." (PMID 28523230, 2017). "In keeping with the role of MMP-9 and TIMP-1 in the pathogenesis of stroke, mild hypothermia provided protection from ischemia/reperfusion injury via decreasing the expression of MMP-9 and TIMP-1." (PMID 26973468, 2016). "In anti-stroke target analysis of the total group, the results showed that IL1B, IL8, JUN, MMP9 and PTGS2 were significantly up-regulated." (PMID 27672514, 2016). "Furthermore, MMP-9 levels were shown to directly relate to stroke infarct volume, a correlation that was observed at 24 h post-stroke, but was apparent as early as 6 h post-stroke, with MMP-9 identified as the only marker that accurately predicted final infarct volume." (PMID 26973468, 2016). "MMP-9 especially is believed to play a major role in BBB disruption during ischemic stroke because ischemic stress induces MMP-9 and the plasma MMP-9 concentration, which strongly correlate with patients’ stroke severity." (PMID 26834557, 2016). "Despite this, controversy remains as to which cells release MMP-9 at the normal and pathological BBB, with even less clarity in the context of stroke." (PMID 26973468, 2016). "Investigation of the role of MMP-9 and neutrophils in cerebral ischemia has taken two approaches, either knockout of MMP-9 or depletion of neutrophils prior to induction of stroke." (PMID 26973468, 2016). "The “Triage® Stroke Panel”, a biochemical multimarker assay, detects Brain Natriuretic Peptide (BNP), D-Dimers (DD), Matrix-Metalloproteinase-9 (MMP-9), and S100β protein generating a Multimarker index of these values (MMX)." (PMID 27247610, 2016). "During stroke, MMP-2 and MMP-9 are up-regulated, leading to increased BBB permeability through degradation of endothelial matrix proteins." (PMID 25914628, 2015). "Stroke-induced damage to the BBB and hemorrhagic transformation are both induced by the activation of the gelatinases, MMP-2 and MMP-9, as demonstrated in animal models and in patients." (PMID 25972779, 2015). "Treatment with rt-PA starting with administration at 20 min after stroke reduced the stroke-induced activation of IL-6, TNF-α, Caspase 3, hsp 32, hsp 70 and MMP-9 significantly in the MCAO." (PMID 24465746, 2014). "MMP-9 reportedly degrades ZO-1, suggesting a link between MMP-9 expression in stroke and BBB leakage." (PMID 25418536, 2014). "MMPs, particularly MMP-9 and MMP-2, are important mediators of vascular dysfunction/remodeling after stroke." (PMID 25147751, 2014).
Stroke (continued). "High levels of both MMP-9 and MMP-13 were detected in the hyperacute phase of stroke and were correlated with an increase in diffusion-weighted imaging lesions within the first 24 h." (PMID 23565108, 2013). "A growing body of experimental and clinical evidence shows MMP-9 plays a major role in BBB disruption in a variety of pathological conditions including CNS infections, stroke, multiple sclerosis and traumatic brain injury." (PMID 23829879, 2013). "The contrasting effects of albumin in stroke and TBI reflect the complexity of the cellular responses to MMP-9." (PMID 22507553, 2012). "Several biomarkers such as S100β, glial fibrillary acidic protein (GFAP), matrix metalloproteinase-9 (MMP-9), and neuron-specific enolase (NSE) have been extensively studied in stroke." (PMID 23028472, 2012). "This system rapidly analyses Brain Natriuretic peptide (BNP), D-Dimers (DD), Matrix Metalloproteinase-9 (MMP-9) and S 100 B protein to estimate-together with a Multimarkerindex (MMX)-the probability of stroke." (PMID 22400994, 2012). "Deletion of MMP-9, or inhibition of MMP-9 activity, improved neurologic function after TBI or stroke." (PMID 22507553, 2012). "This rationale based on the reported positive effects of hyperoxia in experimental stroke, e.g., reduced degradation of BBB components, inhibition of MMP-9 upregulation, and decreased secondary hemorrhage when tPA was given following hyperoxia." (PMID 22273146, 2012). "The triage stroke panel measures BNP, DD, MMP-9, S100 B and generates the Multimarkerindex of these values (MMX)." (PMID 22400994, 2012). "The "Triage® Stroke Panel", a biochemical multimarker assay, detects Brain Natriuretic Peptide (BNP), D-Dimers (DD), Matrix-Metalloproteinase-9 (MMP-9), and S100B protein and promptly generates a Multimarkerindex of these values (MMX)." (PMID 22400994, 2012). "Our previous study on neurovascular protection by S-nitrosylating agents in TBI and stroke shows that GSNO down regulated the expression of inflammatory mediators ICAM-1, ED-1, iNOS, MMP-9, protected the BBB, and improved neurological functions." (PMID 21733162, 2011). "Other authors noted that MMP-9 responses in the acute phase, and afterwards MMP-2 in later phases after stroke." (PMID 21679435, 2011). "Different MMPs are expressed in different conditions and at different times following stroke, with MMP-2 being amongst the first activated, followed by MMP-9 in later stages of inflammation and repair." (PMID 21110846, 2010). "Olmesartan, a AT1 receptor blocker can reduce the reactive upregulation in brain angiotensin II, MMP-2, MMP-9 and membrane type 1-MMP in the ischemic area to improve stroke index score, infarct volume, and cerebral edema in cerebral ischemia model." (PMID 20514206, 2009). "There is an early increase in MMP-9 expression in the microvascular walls after cerebral ischemia and selective inhibition of MMP-9 reduces the brain injury after stroke." (PMID 19497125, 2009). "In rodent models, MMP-9 responses appear to dominate in the acute phase, whereas MMP-2 elevations seem to occur in the delayed phase, days after stroke." (PMID 20514206, 2009). "Within hours after stroke onset, endothelial and inflammatory cells respond to ischemia releasing proteases MMP-2 and MMP-9 that culminate in degradation of the basal lamina and ultimate weakening of the blood brain barrier." (PMID 16846501, 2006). "Among them, MG6 cells expressed high levels of Cxcr2, S100a8, interleukin (IL)‐1β, and matrix metallopeptidase 9 (MMP9), demonstrating a unique “neutrophil‐like” phenotype and were considered to represent a stroke‐specific state of microglia in the aged brain after stroke." (PMID 40843131, 2025). "Additionally, in another study, pro-MMP-9 was significantly lower in patients who presented with a composite endpoint of amaurosis fugax, TIA and stroke." (PMID 40364266, 2025).
Stroke (continued). "According to the study, high levels of MMP-9 are connected to unstable carotid plaques, implying MMP-9 could be targeted in therapies to stabilize plaques and prevent strokes." (PMID 41516038, 2025). "MMP-9 concentrations have also correlated positively with the severity of stroke as determined by the National Institutes of Health and Stroke Scale (NIHSS) after 12 h (r = 0.46, p = 0.01), but not with the NIHSS measured on admission (r = 0.28, p = 0.12)." (PMID 39091977, 2024). "Three of them showed higher MMP-9 levels in AIS patients compared to stroke mimics (p ≤ 0.05), although two studies did not perform statistical comparisons between AIS and stroke mimic patients." (PMID 39091977, 2024). "Furthermore, hNSC transplantation reduces infarct size and proinflammatory factor (TNF-α, IL-6, and IL-1β), matrix metalloproteinase-9 (MMP-9), and MMP-3 expression in aged stroke mice." (PMID 37728582, 2024). "Collectively, these findings demonstrate that MG-specific Nrf2 knockdown leads to augmented MMP3 and MMP9 expression in the ischemic brain, and that may subsequently result in aggravated BBB disruption after stroke." (PMID 39469715, 2024). "Hence, the aim of this study was to assess the prognostic value of MMP-9, TIMP-1, and MMP-9/TIMP-1 ratio, and of the expression of their genes, as markers of recovery in stroke patients." (PMID 38891934, 2024). "This novel herb-based product improves motor control as evaluated using the National Institutes of Health Stroke Score (NIHSS); level of post-stroke disability; and stroke serum biomarkers, such as MMP-9, VCAM-1, and s100β, in patients who experience transient ischemic and minor ischemic stroke." (PMID 39599732, 2024). "Although individual MMP expression had been examined at the prolonged time points, such as 24 h, 5, 7, and even 14 days, post stroke, MMP-9, MMP-3, and MMP-2 had not been compared simultaneously and we chose the 24 h time point to detect acute changes." (PMID 39273389, 2024). "Exploratory clinical trials inhibiting MMP-9, factors expressed mainly by neutrophils, have gained some promising results, demonstrating reduced alteration of BBB and neural tissue damage, both processes important in MS and stroke pathology." (PMID 38790402, 2024). "The expression of MMP-9 in non-stroke hemisphere showed a minimal, non-significant increase in ctl group regardless of ischemic time, while r-tPA-treated mice showed a mild increase at 4 h." (PMID 39273389, 2024). "However, T2DM-BMSC-EXOs treatment has been demonstrated to significantly decrease activated microglia, M1 macrophage, and inflammatory factors MMP-9 and MCP-1 expression in the ischemic brain in T2DM stroke rats." (PMID 38720885, 2024). "Lastly, we predicted 53 potential drugs that may exert neuroprotective effects in early stroke by targeting 5 genes (STAT3, MMP9, AQP9, SELL, FPR1)." (PMID 37180174, 2023). "In the late stages of stroke-induced BBB disruption, MMP-9 expression triggers devastating injury." (PMID 37840921, 2023). "Two days after stroke, MMP-9 and MMP-2 concentrations were significantly higher in ischemic lesions in comparison with non-ischemic lesions and, additionally, an elevated level of MMP-9 was found also in the ischemic penumbra." (PMID 36835040, 2023). "Further research demonstrated that CD47 promotes MMP-9 (matrix metalloproteinase-9) and VEGR (Vascular endothelial growth factor) upregulation after stroke, which contributes to increased inflammatory cell infiltration and aggravated neuro-inflammation in the ischemic brain." (PMID 38125492, 2023). "Simvastatin administered during the first week of IS inhibited the serum MMP-9 activity, although the early treatment with simvastatin (started at first day after stroke onset) influenced neither MMP-9 nor TIMP-1 levels." (PMID 36835040, 2023).
Stroke (continued). "In addition, salidroside reversed the decrease in tight junction proteins (such as claudin-5 and occludin) by inhibiting the activation of MMP-9 (a member of MMPs), which proved the improvement of BBB damage in experimental stroke rat models." (PMID 35462916, 2022). "Taken together, miR-206 may serve as a detrimental factor targeting neurons and vasculature in stroke, potentially involved in BBB breakdown through MMP-9 regulation and thus leading to HT." (PMID 36009063, 2022). "Stroke patients have a significantly higher serum level of MMP-2 and MMP-9 than healthy controls." (PMID 35477576, 2022). "Promising murine studies highlight that recruitment of regulatory T cells improves cognitive function in AD,313,314 promotes microglia-mediated oligodendrogenesis following stroke, prevents Ang II evoked disruption of NVC197 and ameliorates neutrophil MMP-9 mediated BBB breakdown." (PMID 35581998, 2022). "Microglia are also a major source of MMPs after stroke, especially MMP-3 and MMP-9." (PMID 34711943, 2022). "In addition, by using MMP-9–/– mice, several studies confirmed the critical role of this enzyme in the induction of BBB permeability in stroke models and EAE." (PMID 36034148, 2022). "While proteins such as brain natriuretic peptide (BNP), matrix metalloproteinase-9 (MMP9), and glial proteins, including GFAP and S100β, have been identified as potential biomarkers for stroke, accumulating data have explored circulating miRNAs as biomarkers for acute stroke." (PMID 35328807, 2022). "As expected, MMP-9 immunoreactivity was absent in the sham-operated rats and markedly increased in stroke animals." (PMID 35309561, 2022). "Furthermore, HDAC inhibitors, including sodium butyrate and valproic acid, protected against stroke-induced BBB disruption and brain edema by inhibiting MMP9 production, TJ degradation, and NF-kB activation." (PMID 34248961, 2021). "Factors involved in HT of human stroke include a shift in growth factor-beta signaling involving SMAD4, INPP5D, and IRAK3, a disruption of coagulation factors V and VIII, and amphiregulin, a growth factor-beta that regulates MMP-9." (PMID 34054705, 2021). "Therefore, research results show that LXA4ME reduces brain damage after stroke by improving BBB function, reducing MMP-9 expression, and increasing TIMP-1 expression." (PMID 33921615, 2021). "VEGF and MMP‐9 are detrimental to BBB integrity but beneficial for compensatory angiogenesis, whereas PTX3 is beneficial for BBB integrity during the acute phase of stroke but harmful for compensative angiogenic responses during the chronic phase." (PMID 33314664, 2021). "This study aimed to explore whether butylphthalide combined with conventional treatment can change the levels of MMP-9 and VEGF and the NIHSS scores of patients with stroke." (PMID 34987460, 2021). "Immediately after stroke onset, neutrophils migrate and adhere to the brain endothelium through intracellular adhesion molecule 1 (ICAM-1), where they release a large amount of MMP-9 that degrades the basal lamina and TJs holding ECs together." (PMID 33807314, 2021). "They identified higher macrophage infiltration in carotid plaques, obtained from patients operated early after stroke, compared with asymptomatic patients, as well as significantly elevated levels of a set of proinflammatory cytokines and MMP8, MMP9, and MMP2 activity." (PMID 32206187, 2020). "MMP-9 upregulation results in the degradation of tight junction proteins such as ZO-1, occludin, and the basal lamina, ultimately triggering BBB disruption and brain edema in the acute stage of stroke." (PMID 33510620, 2020). "Targeting the COX-2/MMP-9 pathway could represent a promising strategy to reduce brain injury and preserve the integrity of the BBB following stroke." (PMID 32973660, 2020). "In this study, hypertension was associated with increased expression of the cleaved active forms of MMP9 at 12 weeks after stroke, but this was not the case in normotensive animals." (PMID 33214598, 2020).